MAP4 (microtubule associated protein 4)
Diseases named in the same sentence as MAP4 in open-access papers (continued):
Sharing a sentence is not in itself a finding about the gene and the disease.
tumor (11 papers, 2008 to 2025). "The high expression of MAP4 was significantly associated with tumor differentiation (P = 0.034), tumor size (pT, P = 0.005) and lymph node metastasis (pN, P = 0.012)." (PMID 36991467, 2023). "And the ESCC tissues of low FBXW7 along with high MAP4 were significantly associated with tumor differentiation (P = 0.01), tumor size (pT, P = 0.002) and lymph node metastasis (pN, P = 0.029)." (PMID 36991467, 2023). "A significant association was detected between high MAP4 expression and the presence of residual tumour (χ2 = 10.426, df = 2, P = 0.005)." (PMID 30737623, 2019). "In the current study, a significant association was detected between high MAP4 expression and the presence of residual tumour (χ2 = 10.426, df = 2, P = 0.005)." (PMID 30737623, 2019). "The SYNE2 is a protein-coding gene, associated with various neoplasms, while another protein-coding gene, the MAP4, is involved in microtubule dynamics and its disruption may lead to mitotic abnormalities." (PMID 40941618, 2025). "Mutational and transcriptomic level studies revealed significant differences in DNA methylation, single nucleotide polymorphism, and transcript levels between YWHAG and MAP4 in normal tissues compared to tumor tissues, and differential expression of the 2 proteins in immunohistochemistry." (PMID 36705386, 2023). "In conclusion, both MAP4 and Syk were associated with tumour stage." (PMID 30737623, 2019). "In chemotherapy-naïve cases (n = 448), low Syk-c, low Syk-n and low MAP4 also showed significant association with organ-confined status of tumour (Syk-c: χ2 = 10.551, df = 1, P = 0.001; Syk-n: χ2 = 5.041, df = 1, P = 0.025; MAP4: χ2 = 14.322, df = 1, P = 0.000154)." (PMID 30737623, 2019). "With low calpain-1 expression associating with stage 1 tumour, in the current study, low Syk-c and MAP4 expression also related to organ-confined status (Syk-c: χ2 = 9.975, df = 1, P = 0.002; and MAP4: χ2 = 15.402, df = 1, P = 0.000087)." (PMID 30737623, 2019). "Thus, the calpain system, together with Syk-c and MAP4, might be linked with overall survival via their associations with tumour spread." (PMID 30737623, 2019). "The expression of FBXW7 in the TCGA database was lower, and the expression of MAP4 was higher in tumor tissues compared to adjacent tissues, but the difference was not significant." (PMID 36991467, 2023). "The mRNA levels of FBXW7 in GSE53622 were significantly decreased, and MAP4 was significantly increased in tumor tissues compared to adjacent tissues." (PMID 36991467, 2023). "To investigate if ITPN allows the simultaneous generation of biallelic knock-ins carrying different fluorescent tags within each allele, we targeted the SEC61B, MAP4, and HIST1H2BC loci in tumor organoids with both mNeongreen and mScarlet targeting vectors." (PMID 35089911, 2022). "How MAP4, Syk and calpain-1 are involved in tumour cell spreading/migration, and in cellular response to taxane-containing chemotherapy, remains to be elucidated." (PMID 30737623, 2019). "Higher significance was observed for Syk and MAP4 expression, regarding tumour spread, when grouping patients into two broader categories by organ-confined status than grouping by FIGO staging classifications." (PMID 30737623, 2019). "Chromosomal losses and gains regarding 254 driver genes analysed determined losses of SETD2 (43/48) and MAP4 (38/48) at 3p21.31 assigned to Fuhrman grade G1 in 24/26 G1 and 23/26 G1 tumours, respectively, to 17/20 G3 and 13/20 G3 tumours." (PMID 28486536, 2017). "The precise role for MAP4 in tumour sensitivity to taxanes remains to be defined." (PMID 30737623, 2019). "Overall, the current results suggest that Syk, MAP4, and calpain-1 expression are correlated with each other and these proteins may be involved in early stages of tumour spread." (PMID 30737623, 2019).
tumor (continued). "In addition to the staining of tumour cells, Syk and MAP4 staining was observed in areas of tumour-adjacent normal tissue; moreover, Syk staining was also observed in immune cells." (PMID 30737623, 2019). "Moreover, low levels of MAP4 expression extended throughout the tumour mass, whereas in normal epidermis expression was confined to the basal layer." (PMID 18657901, 2008). "As predicted, expression of Lrig1 and MAP4 was markedly decreased in tumours." (PMID 18657901, 2008). "While Lrig1 and MAP4 expression was decreased in tumours, MCSP expression was upregulated." (PMID 18657901, 2008). "Downregulation of two markers, Lrig1 and MAP4, and upregulation of a third, MCSP, correlated with poor differentiation status and increased proliferation in primary tumours." (PMID 18657901, 2008). "Downregulation of MAP4 and Lrig1 and upregulation of MCSP were consistent features of SCC lines and primary tumours." (PMID 18657901, 2008). "We found that MAP4 and Lrig1 were significantly downregulated in oral SCCs, while CD44, which has recently been reported to be a marker of tumour initiating cells in head and neck SCCs, and MCSP were highly upregulated." (PMID 18657901, 2008). "There is no experimental evidence to prove the relationship between MAP4 and tumour radiosensitivity." (PMID 38341398, 2024). "The mRNA levels of FBXW7 in GSE53622 were significantly decreased in tumor tissues compared to adjacent tissues, but there was no obvious trend in MAP4 between tumor and adjacent tissues." (PMID 36991467, 2023). "In tumours, there was a general reduction in MAP4 staining intensity, irrespective of differentiation status." (PMID 18657901, 2008). "The data from the SCC lines make two predictions about marker expression in primary tumours: that markers that are co-expressed in the basal layer of normal epidermis are not co-expressed in SCCs; and that downregulation of MAP4 and Lrig1 is a characteristic feature of SCCs." (PMID 18657901, 2008).
infection (6 papers, 2012 to 2024). The state of being infected such as from the introduction of a foreign agent such as serum, vaccine, antigenic substance or organism. "To further shed light on the role of MT-stabilization in modulating NWS infection, we next explored the possible contribution of MAP4, a MT-associated protein showing rescue-promoting activities during the in vitro assembly of MTs." (PMID 22911759, 2012). "The hypothesis that MAP4 can be a risk factor determining severity of infection is supported by the fact that MAP4 can interact with IL7R mRNA." (PMID 31122248, 2019). "Even though the observed reduction of MAP4 levels upon NWS infection in the LLC-MK2 model is highly suggestive of a host cell shut-off, a virus-induced recruitment of proteases acting against MAP4 cannot be ruled out at the present time." (PMID 22911759, 2012). "Intriguingly, here we report that viral growth in LLC-MK2 cells is significantly improved when MAP4 silencing is established at the beginning of NWS infection." (PMID 22911759, 2012). "Additionally, positive interactors of DCAF11 that were lost upon infection encompass splicing factors THRAP3 and SRSF5, the microtubule-associated protein MAP4, mitochondrial ribosomal protein MRPL12, and the TUFM mitochondrial translation elongation factor." (PMID 39383947, 2024). "Moreover, upon NWS infection we observed a progressive decrease of MAP4 expression in LLC-MK2 cells, whilst in MDCK cells its poor amount was unchanged." (PMID 22911759, 2012). "Finding that LLC-MK2 cells possess high levels of MAP4, we were interested to investigate the effects of MAP4 depletion on NWS infection by using a RNA-mediated RNA interference approach." (PMID 22911759, 2012).
neurodegenerative disease (3 papers, 2023 to 2025). A disorder of the central nervous system characterized by gradual and progressive loss of neural tissue and neurologic function. "MAP4 polymerizes with other microtubule-associated proteins and regulates the properties of microtubules, which are strongly associated with neurodegenerative diseases." (PMID 40943121, 2025).
cardiovascular disease (2 papers, 2020 to 2021). "MAP4 is a unique member of MAPs that is widely expressed in various tissues and cells, and recently, an increasing number of studies have suggested that MAP4 might play an important role in cardiovascular disorders." (PMID 32982783, 2020).
cardiac disease (1 paper, 2025). "Similar to tau, MAP4 aggregates may disrupt cellular homeostasis, and elucidating this mechanism may be a promising therapeutic target for improving cardiac healing function in cardiac disease." (PMID 40678799, 2025).
kidney (1 paper, 2022). "The chromogenic intensity of the Cis group was significantly lower than that of the N Ctrl group, suggesting that the expression of MAP4 was decreased in the cisplatin-induced kidney injury model." (PMID 35844954, 2022).
peripheral nervous system diseases (1 paper, 2021). "We also observed that proteins enriched in GO term of peripheral nervous system disease, including MAP4, MTM1, MYO5A and GDAP1, were significantly increased in T2DM‐MCI patients." (PMID 34528736, 2021).
retinopathy (1 paper, 2022). "Otherwise, it should be indicated that the MAP4 KI mice also developed retinopathy." (PMID 35902952, 2022).
MAP4 also shares sentences with these, for which no sentence is quoted: prostate tumors (3 papers); acute lymphoblastic leukemia (1); alcohol dependence (1); aneurysm (1); arrhythmogenic right ventricular cardiomyopathy (1); autism (1); Burkitt lymphoma (1); colorectal cancer (1); diabetic retinopathy (1); diffuse large B-cell lymphoma (1); dilated cardiomyopathy (1); dwarfism (1); epilepsy (1); Familial adenomatous polyposis (1); gout (1); hepatoma (1); hypertrophic cardiomyopathy (1); idiopathic cardiomyopathy (1); ischemic cardiomyopathy (1); Joubert syndrome (1); lung injury (1); lymphoma (1); microcephaly (1); mucinous tumours (1); non-small cell lung carcinoma (1); renal fibrosis (1); retinal degeneration (1); rheumatoid arthritis (1); schizophrenia (1); Seckel syndrome (1).
A further 5 diseases each share a sentence with MAP4 in 1 paper.